SPI1 (Spi-1 proto-oncogene)
Diseases named in the same sentence as SPI1 in open-access papers (continued):
Sharing a sentence is not in itself a finding about the gene and the disease.
amyloid (7 papers, 2019 to 2025). "We crossbred each mouse model with amyloid-β (Aβ) amyloidosis mouse models to investigate the effects of loss- or gain-of-function of Spi1 on major AD phenotypes in vivo." (PMID 38734693, 2024). "Consistent with the increased levels of Aβ peptides in Spi1+/−;APP/PS1 mice, we detected a 1.76- and 2.59-fold increase in amyloid plaque burden in the cortex and hippocampus, respectively, in Spi1+/−;APP/PS1 mice compared to Spi1+/+;APP/PS1 mice." (PMID 38734693, 2024). "Our data demonstrate that Spi1 knockdown exacerbates multiple pathological hallmarks, including Aβ aggregation, amyloid plaque accumulation, and gliosis." (PMID 38734693, 2024). "Here, we show that the knockdown of Spi1 expression significantly exacerbates insoluble amyloid-β (Aβ) levels, amyloid plaque deposition, and gliosis." (PMID 38734693, 2024). "Contrary to a previous in vitro report, we found that Spi1-knockdown increased gliosis, whereas Spi1-overexpression decreased, gliosis in amyloidosis mouse models." (PMID 38734693, 2024). "This suggests that Itgam/CD11b and Spi1/PU.1 genes may play a role in regulating the change in microglia number in response to amyloid plaques, given the strong correlation between the expression of these genes and amyloid pathology." (PMID 32274467, 2019).
colon carcinoma (7 papers, 2021 to 2025). "Upregulation of SPI1 or SPIB was found to be associated with poor prognosis in patients suffering from colon cancer." (PMID 34841706, 2021). "Literature reports that SPI1 interacts with IRF1 or TIMP1 to regulate the sensitivity of colon cancer to ferroptosis." (PMID 41372608, 2025). "There is a rich literature available suggesting that SPIB promotes trans-activation of SPI1 to increase glycolytic gene expression and drive the glycolytic process, proliferation, and invasiveness of colon cancer cells." (PMID 35969172, 2022). "In colon cancer specimens, a positive expression correlation was noted between SPI1 and HK2 (R = 0.1067, p < 1 × 10−4) or PGK (R = 0.4026, p < 1 × 10−4)." (PMID 34841706, 2021). "In this study, based on evidence from co‐IP and BiFC assays, we found that ETS domains of SPIB and SPI1 were essential for their physical interaction in colon cancer cells." (PMID 34841706, 2021). "To understand SPI1's impact on glycolysis, we chose colon cancer cell lines LoVo and HCT116 (representing middle SPI1 levels) as models." (PMID 34841706, 2021). "Above data suggested that SPI1 was elevated and facilitated glycolytic gene expression in colon cancer." (PMID 34841706, 2021). "In co‐culture and conditional medium assays, TANs facilitated glycolytic process, growth and invasion of colon cancer cells, while their derived EVs displayed a high level of SPI1 transcript." (PMID 34841706, 2021). "In the current study, our data demonstrated that transcription factor SPI1 was elevated in cancerous cells and stroma of colon cancer, especially in neutrophils, which was consistent with previous findings that SPI1 is involved in differentiation of neutrophils." (PMID 34841706, 2021). "Higher SPI1 levels were noted in TANs, than those of PNs or colon cancer cells." (PMID 34841706, 2021). "In the current study, we discover that SPI1 is substantially expressed within tumoural tissues as well as stroma of colon cancer, while neutrophils deliver SPI1 mRNA to cancer cells via extracellular vesicles (EVs), leading to abnormal expression of SPI1 in cancer cells." (PMID 34841706, 2021). "Importantly, SPIB facilitated transactivation of SPI1 to increase expression of glycolytic genes and drove glycolytic process, proliferation and invasiveness of colon cancer cells." (PMID 34841706, 2021). "Immunohistochemistry indicated that when compared with adjacent normal tissues, higher immunostaining of SPI1 was observed within cancerous cells and stroma of clinical colon cancer specimens, whereas elevated SPIB expression was mainly localized within cancerous tissues." (PMID 34841706, 2021). "Western blotting as well as real‐time qRT‐PCR measurement showed upregulation of SPI1 and SPIB protein in colon cancer specimens, while their transcript levels were reduced or elevated than those in normal counterparts, respectively." (PMID 34841706, 2021). "BiFC and co‐IP assays indicated that SIP‐11 treatment abolished the interaction between SPI1 and SPIB in colon cancer cells." (PMID 34841706, 2021). "Importantly, upregulation of SPI1 (p = 2.2 × 10−3), HK2 (p = 1.0 × 10−2) or PGK (p = 2.9 × 10−4) was found to be related with a poor survival in colon cancer patients." (PMID 34841706, 2021).
Insulin resistance (7 papers, 2011 to 2025). Increased resistance towards insulin, that is, diminished effectiveness of insulin in reducing blood glucose levels. "Moreover, the upregulation of Spi-1 proto-oncogene (SPI1, or PU.1) in adipocytes can cause insulin resistance by stimulating reactive oxygen species production and inflammatory cytokine gene expression." (PMID 34516309, 2021). "PCOS group also exhibited an increased expression of androgen-mediated genes (SPI1 and ETS transcription factors) and genes associated with hyperlipidemia and insulin resistance (TNFRSF1B)." (PMID 40790236, 2025). "SPI1 is primarily expressed in bone marrow cells and lymphocytes, and correlates positively with insulin resistance and inflammation in NASH patients, making it a potential therapeutic target." (PMID 39350187, 2024). "Even seemingly unrelated proteins, suchas spleen focus forming virus (SFFV) proviral integration oncogene spi1, may beconnected to the problem of insulin resistance." (PMID 22442648, 2011).
viral infection (7 papers, 2015 to 2026). "It is possible that severe and chronic peripheral inflammation caused by persistent bacterial or viral infection may enhance certain genetic vulnerabilities for AD, including those conferred by APOE ε4, as well as particular SPI1 and CD33 genotypes." (PMID 36550123, 2022). "Nine TFs such as DUX, SPI1, and ERG targeted the total eight genes, and may collaboratively regulate the downstream pathways of metabolic and virus infection, which are the pivotal paths in the SGA." (PMID 39687015, 2024).
allergic disease (6 papers, 2015 to 2024). An immune response that occurs following re-exposure to an innocuous antigen, and that requires the presence of existing antibodies against that antigen. "Considering that Th2-related genes such as Tnsf4 and Ccl22 are also transactivated by PU.1 in DCs, Spi1 knockdown may be a favorable strategy for allergic diseases." (PMID 30718772, 2019).
Autoimmunity (6 papers, 2020 to 2025). The occurrence of an immune reaction against the organism's own cells or tissues. "Biologically and directionally consistent with these findings, in our analysis, the meta-analysis lead SNP rs3740688-T was associated with decreased autoimmune/autoinflammatory disease (Hashimoto’s thyroiditis) risk, increased SPI1 expression and increased prostate cancer risk." (PMID 40428397, 2025). "Of note, IRF4, MEF2C, and SPI1 have been reported to be crucial in the development of autoimmunity." (PMID 35350715, 2022).
chronic myelogenous leukemia (6 papers, 2010 to 2024). "With SPI1 appearing to be a specific modulator in macrophages, K-562 (human chronic myelogenous leukemia cell line) cells instead rely upon multiple TFs, from AP-1 to FOXJ3." (PMID 38343549, 2024). "Likewise, expression of SPI1 is severely reduced in human patients with chronic myeloid leukemia due to aberrant promoter methylation in tumor cells." (PMID 27506447, 2016).
depression (6 papers, 2020 to 2025). "Finally, the genomic region surrounding the SPI1 gene (in which variant rs3740688 maps) has been previously associated with cognitive traits (intelligence, depression) and, with lower evidence, with kidney disease and cancer." (PMID 34992629, 2021). "Additionally, SPI1 has been identified as a shared gene between PD and major depressive disorder, while ITGB2 is upregulated in patients with unipolar depression." (PMID 40271183, 2025). "In addition, using postmortem tissues, we reported correlations between BDNF propeptide in the brain and spleen, and a negative correlation between CSF1R and transcription factor PU.1 (SPI1), suggesting a role for the brain–spleen axis in psychiatric disorders such as depression." (PMID 33963284, 2022). "Identification of SPI1 and MAPT as genes for AUD are good examples of pleiotropy and/ or causal links between the alcohol intake and susceptibility to AUD, other psychiatric disorders (e.g., depression), and even Alzheimer’s disease and other neurodegenerative diseases." (PMID 34417470, 2021).
Stroke (6 papers, 2016 to 2025). Sudden impairment of blood flow to a part of the brain due to occlusion or rupture of an artery to the brain. "For example, the lncRNA FTX acts as a sponge for miR-342-3p to regulate SPI1 expression levels, enhancing angiogenesis in stroke." (PMID 39847586, 2025). "In agreement with our findings, transcriptomic analysis of astrocytes has shown Stat3, Sp1, and Spi1 as the most significant transcription factors in stroke." (PMID 35250546, 2022).
gastroenteritis (5 papers, 2013 to 2023). An inflammatory disorder that affects the upper and lower gastrointestinal tract. "Fasting dramatically interrupted infection and subsequent gastroenteritis by suppressing Salmonella’s SPI-1 virulence program, preventing invasion of the gut epithelium." (PMID 34352037, 2021). "Strains of the various Salmonella enterica serovars cause gastroenteritis or typhoid fever in humans, with virulence depending on the action of two type III secretion systems (Salmonella pathogenicity island 1 [SPI-1] and SPI-2)." (PMID 27920299, 2017). "SPI-1 effectors are required for the invasion of epithelial cells and intestinal inflammation, which results in gastroenteritis." (PMID 23950998, 2013). "Notably, we found that fasting blocked S. Typhimurium’s ability to invade the intestinal epithelium through suppression of SPI-1-based cellular invasion, thereby preventing gastroenteritis development." (PMID 34352037, 2021). "In human infections, the roles of SPI-1 and SPI-2 have not been defined as clearly, though a study in China has indicated that clinical isolates from a food-borne disease outbreak of S. Senftenberg lacking SPI-1 were still able to cause gastroenteritis." (PMID 31214517, 2019). "Our SPI-1 results are not in agreement with a study in China which indicated that SPI-1 was not required for human gastroenteritis since two S. Senftenberg strains isolated from a food-borne disease outbreak were SPI-1 deficient." (PMID 31214517, 2019). "To test this, we examined the expression of SPI-1 virulence factors, since they are required for Salmonella to infect host IEC and trigger gastroenteritis." (PMID 34352037, 2021).
osteopetrosis (5 papers, 2018 to 2024). Osteopetrosis, also known as marble bone disease, is a descriptive term that refers to a group of rare, heritable disorders of the skeleton characterized by increased bone density on radiographs. "In the Erythroblast transcription factor (ETS) family, Spi1 proto-oncogene (PU.1) is unique to hematopoiesis and it has been shown that when mice with PU.1 deletion have no OCPs at all, osteopetrosis occurs." (PMID 38338876, 2024).
systemic lupus erythematosus (5 papers, 2014 to 2024). An autoimmune multi-organ disease typically associated with vasculopathy and autoantibody production. "MiRNA-569 has been associated with a functional polymorphism in the 3'-untranslated region of SPI1 with systemic lupus erythematosus." (PMID 32692745, 2020). "For chronic systemic autoimmune disease, systemic lupus erythematosus (SLE), SPI1 overexpression is suggested to have a role in its pathogenesis." (PMID 24991086, 2014).
typhoid fever (5 papers, 2009 to 2021). A bacterial infectious disorder contracted by consumption of food or drink contaminated with Salmonella typhi. "This correlates well with published observation that SPI-1 is dispensable for S. Gallinarum to successfully cause fowl typhoid." (PMID 31998655, 2019). "Moreover, S. enterica mutants in ssaV or any of SPI1-TTSS genes has been efficiently used in preparation of vaccines against typhoid fever or to induce chemokines." (PMID 34946165, 2021).
acute leukemia (4 papers, 2016 to 2022). A clonal (malignant) hematopoietic disorder with an acute onset, affecting the bone marrow and the peripheral blood. "As a of member of the ETS family of transcription factors, the proto-oncogene SPI1 was initially considered to be one of the important causative genes in acute leukemia." (PMID 35237521, 2022). "To investigate whether the fusion proteins target a common transcription factor network we performed motif enrichment analysis on their binding sites, using weight matrices of AML1/RUNX1, C/EBPA, the ETS factor SPI1, GATA and TAL1, all transcription factors reported to be mutated in acute leukemias." (PMID 28030795, 2017).
agammaglobulinemia (4 papers, 2022 to 2025). A decreased level of serum immunoglobulins. "In summary, we report the first Chinese case of PU.1 deficiency caused by a novel SPI1 nonsense variant, confirming the critical role of PU.1 haploinsufficiency in human agammaglobulinemia." (PMID 41394874, 2025). "Since PU.MA represents a newly described form of agammaglobulinemia, our case expands the spectrum of manifestations associated with SPI1 mutation." (PMID 38500873, 2024). "Our finding reinforces the need to include SPI1 in diagnostic panels for agammaglobulinemia." (PMID 41394874, 2025). "The first report identified six unrelated individuals with agammaglobulinemia harboring SPI1 variants that destabilized the PU.1 protein, impaired its nuclear localization, and reduced chromatin accessibility, resulting in developmental arrest of B cells and loss of dendritic cells." (PMID 41394874, 2025). "PU.1 deficiency, also known as Autosomal Dominant Agammaglobulinemia-10 (AGM10), is a rare primary immunodeficiency caused by mutations in the SPI1 gene, leading to B cell deficiency and hypogammaglobulinemia." (PMID 41394874, 2025). "This case highlights the diagnostic value of whole-exome sequencing (WES) in agammaglobulinemia cases of unknown etiology following negative panel results, while also prompting the critical need for commercial assays to undergo regular updates to incorporate newly validated genes like SPI1." (PMID 41394874, 2025).
glioblastoma (4 papers, 2015 to 2025). The most malignant astrocytic tumor (WHO grade IV). "SPI1 may also be a potential biomarker or therapeutic target for glioblastoma; however, this requires further confirmatory study." (PMID 25514975, 2015). "Conversely, SPI1-induced downregulation of FTO in glioblastoma (GBM) promotes tumor growth by altering the processing of pri-miR-10a in an m6A-dependent manner." (PMID 40271153, 2025). "SPI1 may influence the development of glioblastoma through regulation of functional immune cells." (PMID 25514975, 2015).
myocardial infarction (4 papers, 2023 to 2025). Gross necrosis of the myocardium, as a result of interruption of the blood supply to the area, as in coronary thrombosis. "Our analysis also identified the TFBS for Spleen focus forming virus proviral integration oncogene (SPI1), known for its heightened expression post-myocardial infarction." (PMID 39838281, 2025). "A previous study has shown that SPI1 upregulation activated the TLR4/NFκB axis and aggravated myocardial infarction." (PMID 36675183, 2023). "SPI1 upregulation reportedly stimulated the TLR4/NFκB axis and aggravated myocardial infarction." (PMID 39145311, 2024).
non-small cell lung carcinoma (4 papers, 2022 to 2025). A group of at least three distinct histological types of lung cancer, including non-small cell squamous cell carcinoma, adenocarcinoma, and large cell carcinoma. "In non-small cell lung cancer, SPI1 exerted an oncogenic role via upregulation of lncRNA SNHG6 and miR-485-3p/VPS45 axis." (PMID 35945192, 2022). "Moreover, SPI1 promotes lncRNA SNHG6 transcription by binding to the SNHG6 promoter, thereby promoting the migration and invasion of non-small cell lung cancer (NSCLC) cells." (PMID 35771155, 2022).
osteosarcoma (4 papers, 2022 to 2025). A usually aggressive malignant bone-forming mesenchymal neoplasm, predominantly affecting adolescents and young adults. "In this study, we revealed a significant association between SPI1 mRNA levels and the prognosis of osteosarcoma patients, indicating its potential as a predictive factor." (PMID 39062086, 2024). "We hypothesized that Rhizoma Paridis total saponins (RPTS) exert anti-osteosarcoma effects by inducing ferroptosis through inhibition of the SPI1/LCN2 axis." (PMID 40636695, 2025). "Furthermore, our findings substantiate the potential role of SPI1 as a transcription factor in the regulation of the two central genes involved in osteosarcoma development." (PMID 39062086, 2024). "Therefore, investigating whether RPTS induces ferroptosis in OS cells via the SPI1/LCN2 axis could provide valuable mechanistic insights and identify novel therapeutic targets to overcome ferroptosis resistance in osteosarcoma." (PMID 40636695, 2025). "Although LCN2 has been reported to be involved in iron homeostasis and immune regulation in various types of cancer, its function in osteosarcoma remains insufficiently studied, and its role as a downstream target of SPI1 in the regulation of ferroptosis has not been clearly elucidated." (PMID 40636695, 2025).
ovarian carcinoma (4 papers, 2021 to 2025). A malignant neoplasm originating from the surface ovarian epithelium. "In conclusion, MIR503HG acted as a tumor suppressor lncRNA in ovarian cancer by suppressing transcription factor SPI1-mediated transcriptional activation of TMEFF1." (PMID 35771155, 2022). "Mechanism researched showed that MIR503HG affected the transcriptional regulation effect of SPI1 on the downstream gene TMEFF1 by interacting with the SPI1, thereby suppressing the tumorigenicity of ovarian cancer cells." (PMID 35771155, 2022). "Among these transcription factors, we noticed that SPI1 was reported to promote malignant progression of ovarian cancer." (PMID 35771155, 2022). "MIR503HG inhibited SPI1-mediated transcriptional activation of TMEFF1 by binding to SPI1, and suppressed the expression of TMEFF1, thus hindering the progression of ovarian cancer." (PMID 35771155, 2022). "SPI1, the key transcription factor regulating KIAA1429, forms a SPI1–KIAA1429–ENO1 axis that drives metabolic reprogramming, connecting m6A-mediated epigenetic changes to TME remodeling and ovarian cancer aggressiveness." (PMID 40986143, 2025). "MIR503HG could bind to the transcription factor SPI1 to prevent SPI1 from binding to the TMEFF1 promoter region, thereby suppressing the tumorigenicity of ovarian cancer cells." (PMID 35771155, 2022).
pancreatic cancer (4 papers, 2011 to 2025). "SPI1 is increased in pancreatic cancer and has been tied to the activation of the WNT signaling pathway, along with other cancer pathways." (PMID 41281751, 2025).
cardiac hypertrophy (3 papers, 2012 to 2021). "Further, an RNA sequencing study examining cardiac hypertrophy demonstrated that SPI1 was significantly up-regulated in the pathogenesis of adverse myocardial remodeling." (PMID 31850068, 2019). "Interestingly, SPI1 has not been reported in cardiac hypertrophy so far." (PMID 34362365, 2021).